ATR (ATR checkpoint kinase)
Diseases named in the same sentence as ATR in open-access papers (continued):
Sharing a sentence is not in itself a finding about the gene and the disease.
tumor (continued). "Cisplatin also induced stronger expression of immune-related and inflammation-related genes in tumor cells, potentially through the ATR DNA damage transducer." (PMID 40370874, 2025). "In this context, reduced ATR levels are tumor-prone due to partial DNA damage response defects leading to increased genomic instability." (PMID 40012043, 2025). "The potent and selective ATR inhibitor (ATRi) tuvusertib (M1774) has been shown to inhibit tumor cell proliferation and viability and is currently in clinical trials." (PMID 41417226, 2025). "ATR inhibitors have been shown to enhance cisplatin sensitivity and reduce resistance in tumour cells." (PMID 40859871, 2025). "Functionally, RECQL4 knockdown sensitizes tumor cells to ATR inhibition, suggesting a potential therapeutic vulnerability in the clinical setting and possibly, a diagnostic role of RECQL4 IHC for treatment selection." (PMID 41317405, 2025). "By impairing ATR function, AZD6738 disrupts the repair of replication-associated DNA lesions, thereby sensitizing tumor cells to DNA-damaging agents such as platinum compounds and PARP inhibitors." (PMID 40869030, 2025). "In an orthotopic breast cancer model, co-targeting ATR and Wee1 led to tumor-selective synthetic lethality, with tumor remission and metastasis impairment." (PMID 40422251, 2025). "BOLD-100 synergizes with AZD6738, an ATR inhibitor, to enhance anti-tumor efficacy compared to either agent alone in both in vitro and in vivo models." (PMID 40514666, 2025). "Our work provides new clues to the underlying mechanisms of tumor resistance and strong evidence validating the AEP/ATR axis as a novel predictive biomarker and therapeutic target for the stratification and treatment of radioresistant BC patients." (PMID 40012043, 2025). "We previously showed that RS score correlates to ATR inhibitor responsiveness and concluded that both RS and ATR signalling capacity determines tumour viability." (PMID 40442403, 2025). "Targeting the ATR pathway holds great promise for anticancer therapy, as tumor cells under substantial replication stress rely heavily on ATR for their survival." (PMID 39920847, 2025). "We found that in CRC-PM mouse models, ATR inhibition in combination with oxaliplatin and anti-PD-1 immunotherapy completely cures and also protects against tumor rechallenge." (PMID 40139833, 2025). "We concluded that ATR inhibition in combination with oxaliplatin and anti-PD-1 immunotherapy improves tumor control and also provides long-term protection against disease recurrence." (PMID 40139833, 2025). "In preclinical models, combining ATR inhibition with DNA-damaging drugs dramatically increases tumor cell mortality." (PMID 41374970, 2025). "Inhibiting the ATM/Chk2 and ATR/Chk1 axes can sensitize tumor cells to DNA-damaging agents, particularly in tumors with DDR deficiencies." (PMID 40422251, 2025). "Dysregulated ATR expression can promote tumor progression and confer resistance to diverse anticancer therapies." (PMID 41409249, 2025). "Experimental evidence has shown that ATR expression and activation are closely correlated with tumour stage, mitotic index, vascular invasion, and patient prognosis." (PMID 40859871, 2025). "Tumor-bearing mice were left untreated or treated with Olaparib (PARPi), ATR inhibitor (AZD6738), or ionizing radiation (2 Gy × 4 or 8 Gy × 1)." (PMID 40630542, 2025). "ATR protein expression exhibits inter-tumor cell variations and a significant variation between the two entities." (PMID 40088750, 2025). "HNSCC cell lines the gene copy number of ATR as determined by qRT-PCR is increased, reflecting an aneuploidy as often seen in tumor cells." (PMID 40088750, 2025).
tumor (continued). "The study emphasizes the relevance of CAF interference with ATR-Chk1 signaling, thereby abrogating G2/M arrest and promoting mitotic catastrophe in tumor cells." (PMID 40650030, 2025). "Its synergistic interaction with ATR inhibitor in vitro and its enhanced anti-tumor efficacy offer a novel combination strategy for PDAC treatment." (PMID 40514666, 2025). "The aim was to assess the model’s ability to generate heterogeneous TGI responses to PARP and ATR inhibitors based on distinct tumour characteristics." (PMID 39875558, 2025). "These alterations render tumor cells highly dependent on ATR for genomic stability, and thus exceptionally sensitive to ATR inhibition." (PMID 40869030, 2025). "The current evidence points to potential therapeutic opportunities arising from exploiting SMUG1-mediated BER to induce synthetic lethality in combination with PARP and ATR inhibitors, particularly in BRCA1/2-deficient tumours." (PMID 41394509, 2025). "Meanwhile, its combination with durvalumab aims to exploit the immunomodulatory effects of ATR inhibition, such as enhanced tumor immunogenicity and increased T-cell infiltration, as previously shown in DDR-deficient tumors." (PMID 40869030, 2025). "ATR inhibitors (ATRi) mediate their anti-tumour activity by forcing tumour cells to enter into mitosis, subsequent to the impairment of the ATR-dependent surveillance of the G2/M cycle checkpoint." (PMID 41188872, 2025). "ATR inhibitors selectively suppress tumor growth by potently blocking ATR kinase activity, thereby disrupting DDR and impairing cell-cycle regulation." (PMID 41409249, 2025). "Supporting this role, studies have shown that ATR inhibition disrupts homologous recombination mechanisms necessary for telomere maintenance in ALT-positive tumours, leading to genomic instability and eventual cell death." (PMID 40256842, 2025). "The three key DNA repair pathways ATM, ATR, and DNA-PK act as core monitors of DNA damage response, significantly influencing tumour development and treatment outcomes." (PMID 40256842, 2025). "It was also reported that ATR-mutant tumors generate a pro-inflammatory microenvironment that promotes tumor growth by regulating the immune responses." (PMID 40940791, 2025). "ATR is particularly activated in many tumours in response to replication stress, often triggered by proto-oncogenes, for instance, Ras, Myc, and Cyclin E, leading to dysregulated cell cycle progression and increased cellular proliferation." (PMID 40256842, 2025). "ATM and ATR are critical kinases in the DDR process, and disruptions in their signaling pathways are closely associated with tumor cell chemosensitivity." (PMID 41473689, 2025). "The expression of PAX3-FOXO1 has been shown to increase tumor replication stress and increase reliance on the ATR/CHK1 repair pathway, making ATR pathway molecules potential therapeutic targets." (PMID 38730598, 2024). "In summary, the preclinical data demonstrate a new strategy of tumor‐targeted delivery of ATR inhibitors with significant potential of enhancing the therapeutic index." (PMID 38976561, 2024). "In addition, previous studies have investigated the role of ATR inhibition as a means of increasing the tumor mutational burden and the production of neoantigens, which may improve the sensitivity to immune checkpoint inhibitors due to elevated antigen presentation." (PMID 38474014, 2024). "We confined further investigations including primary tumor cultures derived from freshly resected tumor material to one ATR inhibitor due to restricted material and restricted cell number in primary cultures (compared with long-term cell cultures)." (PMID 38475864, 2024).
tumor (continued). "The patient’s tumor was found to contain somatic mutations in APC (p.Q1549*), APC (p.R904fs), SMAD4 (p.R135*), SMAD4 (p.A190fs), ATR (p.F134fs) and KRAS (p.G12D)." (PMID 38243056, 2024). "Thirdly, LINC-PINT exerts regulatory control over specific pathways, such as the ATM/ATR-Chk1/Chk2 pathway, significantly influencing tumor cell DNA repair mechanisms." (PMID 38553526, 2024). "Combining auranofin and the ATR inhibitor was well tolerated and synergistically decreased tumor growth along with severe replication stress and excessive DNA breakage, reminiscent of replication catastrophe and late-stage apoptosis in vivo." (PMID 39001381, 2024). "Inhibition of DDR components such as ATR have been shown to facilitate innate immunity responses against tumours and are being explored clinically in combination with immune checkpoint inhibitors (ICIs) (clinicaltrials.gov)." (PMID 38227740, 2024). "Overall, ATR inhibitors exert anti-tumor effects by promoting apoptosis induced by DNA damage and enhancing tumor immunity." (PMID 39103941, 2024). "In summary, our data demonstrate that BLM-induced MHC-I upregulation in tumor cells relies on ATM/ATR–NF-κB activation." (PMID 39106105, 2024). "CHK1 inhibition compromises the growth of tumors overexpressing oncogenic Ras or Myc, and tumor formation is significantly reduced in Eμ-myc mice expressing mutant ATR." (PMID 38530355, 2024). "Upregulation of NK cell activating NKG2D ligands by DNA damage sensing proteins ATM and ATR, lead to NK cell activation against tumor cells." (PMID 38253555, 2024). "Mechanistically, the treatment of drugs induces DNA double-strand breaks in tumor cells, causing the activation of ATM and ATR." (PMID 39045048, 2024). "We showed that both photons and protons were effective at delaying tumor growth when combined with ATR inhibition on day 7 after irradiation." (PMID 39235982, 2024). "Cell viability and apoptosis analyses were performed to examine the anti-tumor activity of ATR inhibitors combined with cisplatin." (PMID 38827321, 2024). "Elevated ATR protein levels in breast tumors are more likely to be seen in patients with advanced tumor stage and increased occurrence of lymphovascular invasion." (PMID 38539474, 2024). "Preclinical data have identified multiple cancer-related phenotypes sensitizing tumor cells to monotherapy ATR inhibition (ATRi)." (PMID 37934611, 2024). "Combined ATR inhibition and ablative radiotherapy inhibited tumor growth and improved survival in mice." (PMID 39487895, 2024). "We also noted that ATR inhibition in combination with radiation was effective in delaying 4T1 tumor growth and extending survival in vivo." (PMID 39235982, 2024). "A significant mortality of tumor cells has been achieved through the combination of Ras activation and total ATR inhibition." (PMID 37511442, 2023). "These considerations have prompted the development of multiple ATR inhibitors which have been shown to potentiate the anti-tumor activity of diverse genotoxic agents including ionizing radiation and cytotoxic drugs." (PMID 37126127, 2023). "Mechanistically, ATR inhibition by AZD6738 appears to block radiation-induced PD-L1 upregulation on tumor cells, thereby reducing the number of tumor-infiltrating regulatory T cells (Tregs)." (PMID 37420037, 2023). "Elimusertib is an oral, highly selective ATR inhibitor with preclinical evidence of anti-tumor activity in cell lines with DDR defects." (PMID 36604210, 2023). "ATR inhibition not only induces tumor growth arrest and apoptosis but also promotes cytosolic DNA formation and immunogenic cell death by replication stress." (PMID 37109350, 2023).
tumor (continued). "EPCAM+, EPCAM− and EPCAM−Rhoj-KO tumour cells similarly increased the level of phosphorylated ATM/ATR substrates after cisplatin/5FU administration, showing that RHOJ does not control ATM and ATR activation after chemotherapy." (PMID 36949199, 2023). "It is suggested that the combination of a WEE1 inhibitor and an ATR/ATM inhibitor can enhance the anti-tumor efficacy in insensitive tumor cells." (PMID 37305685, 2023). "Our study focused on the pathogenic mutations of ATM and ATR, as both genes are from the PIKK family that is critically involved in DNA damage repair in normal cells as well as tumor cells." (PMID 38041093, 2023). "The combination of olaparib and the ATR inhibitor AZD6738 inhibited tumor growth significantly in mice together with radiation therapy." (PMID 38136299, 2023). "The double-positive cells of ATR and scaRNA2 were found to be more prevalent in radioresistant tumours." (PMID 37775817, 2023). "The identification of ATR’s common and unique roles in tumor cells vs. normal cells would provide the first step to identify tumor-specific vulnerability and minimize the toxicity of ATR inhibition." (PMID 37336885, 2023). "The ATR pathway plays an important role in the survival of these tumor cells, and several studies have shown that blocking this pathway has a preferentially lethal effect on cells with high levels of oncogene-induced replication stress." (PMID 37511442, 2023). "It was also shown in this model that the induction of senescence, tumor survival and tumor persistence is dependent on ataxia telangiectasia and Rad3-related protein (ATR) involved in DNA damage/repair." (PMID 37273928, 2023). "In vitro data also indicate that CCL2, CCL5, and CXCL10 were increasingly expressed by tumor cells after ATR inhibition plus RT." (PMID 37420037, 2023). "In general, there are few studies on the pharmacology and clinical application of ATR in anti-tumor, and more studies are needed to investigate the effective components, pharmacological effects and molecular biological mechanisms of ATR in anti-tumor." (PMID 37007031, 2023). "IHC staining and quantitative analysis revealed that the phosphorylation of ATR and Chk1 and the expression of Rad51 were inhibited in tumours derived from the scaRNA2 KD cells." (PMID 37775817, 2023). "Our results suggest that upregulated ATR expression is a critical determinant of survival under KRASG12V-induced RS, adding an unanticipated dosage-dependent function of ATR to the tumor initiation step." (PMID 37591859, 2023). "By utilizing the GDSC database, we found that cluster 1 was more sensitive to the VE‐822, which reduced tumor cell survival by attenuating the ATR signaling pathway." (PMID 37502611, 2023). "Fifth, tumor cells that rely on the alternative lengthening of telomeres (ALT) pathway are also more sensitive to ATR disruption due to ATR’s role in the homologous recombination reactions that maintain these telomeres." (PMID 37511442, 2023). "In AML, induction of senescence as well as tumor survival and chemotherapy persistence are dependent on ATR activity." (PMID 37208719, 2023). "Some greater than additive responses were observed in several complex tumor spheroid models for the combination of topotecan or trabectedin with either ATR inhibitor." (PMID 37637936, 2023). "Similar to the chemoresistance-induced senescence resilient phenotype where ATR catalytic activity enables the induction of this cellular state, tumor survival and persistence, ATR was also involved in the PRLR-mediated resistance to cytarabine." (PMID 37208719, 2023).
tumor (continued). "We measured the levels of DNA damage markers such as p-ATR and p-Chk1 in the tumor lysates by immunoblotting analysis." (PMID 36675341, 2023). "In this study, the inhibitor of CDC7 increased DNA replication stress and then sensitized tumor cells to ATR or CHK1 inhibitors, respectively." (PMID 37153782, 2023). "ATR inhibition can also promote efferocytosis, where apoptotic tumor cells are engulfed by phagocytes such as dendritic cells." (PMID 37346039, 2023). "Inhibitors of the DNA damage signaling kinase ATR increase tumor cell killing by chemotherapies that target DNA replication forks but also kill rapidly proliferating immune cells including activated T cells." (PMID 36810257, 2023). "Collectively, these findings indicate that the combination BRD4i with ATR inhibition, promotes significant tumor regression and increased survival in ARID1AMUT tumors, compared to ARID1AWT models." (PMID 37841875, 2023). "CHK1 inhibitors can well inhibit the protective effect of ATR/CHK1 pathway on MYCN positive tumor cells." (PMID 36311753, 2022). "M6620 has shown some promise as a monotherapy with pre- and post-treatment tumor biopsies demonstrating a reduction in CHK1 phosphorylation (a biomarker of ATR activity)." (PMID 36420962, 2022). "The prolonged control of mPTCL tumor progression in vivo supports the use of ATR inhibition as a single agent for the treatment of the GATA3 subgroup of PTCL." (PMID 35510955, 2022). "Pharmacological inhibition of DNA damage signaling kinases exhibited a specific response profile, with ATR- selective inhibitors showing enhanced replication stress-dependent anti-tumor activity." (PMID 35879366, 2022). "Analysis for the ATR expression in LUAD patients by single-cell sequencing data, we found ATR expression of tumor patients at high level in immune cells when compared with normal patients, but the expression of ATR in stromal cells has the opposite result." (PMID 35712480, 2022). "Taken together, our results provide support for inhibiting E2F activity in combination with ATR inhibition as a promising strategy to provoke catastrophic levels of replication stress in tumor cells that deserves further investigation." (PMID 36230876, 2022). "Even though results of clinical trials with ATR inhibitors in adults have shown promising single agent antitumor activity in various tumor entities, some patients progress or relapse after some time." (PMID 35879366, 2022). "Inhibition of ATR-related signaling pathways increases cell apoptosis and effectively improves tumor radiosensitivity." (PMID 35875060, 2022). "The high levels of DNA replication stress result in addiction to ATR/CHK1 signalling since this allows MYC driven tumour cells to survive high levels of genomic instability." (PMID 36240065, 2022). "Previous results from our and other groups suggested that induction of DDR featuring ATM/ATR pathway activation was a prominent characteristic of the CX-5461 actions in tumor cell lines and in cardiovascular cells." (PMID 36386132, 2022). "Overexpression of LINC00312 combined with exposure to irradiation decreased levels of p-ATM, p-ATR, p-Chk1, and p-Chk2, which play a crucial role in DNA damage checkpoint control and tumor inhibition." (PMID 36294743, 2022). "Inhibition of cell cycle checkpoint ATR offers molecular differentiation between tumor and normal cells, thereby leading to synergistic anticancer effects." (PMID 35458687, 2022). "Owing to their ability to trigger cell-cycle arrest and promote DNA repair through their downstream targets, ATM and ATR inhibitors are considered to improve clinical outcomes of tumor treatment in combination with radiotherapy." (PMID 36230796, 2022). "There is evidence that ATR inhibitors are efficient in the treatment of ARID1A- tumor cells, however clinical verification of the concept is still lacking." (PMID 36249060, 2022).